COMTD1 (catechol-O-methyltransferase domain containing 1)
Description:
Putative O-methyltransferase.
Synonyms: FLJ23841; MT773
Tractability: Small molecule: it has a high-quality binding pocket. Antibody: UniProt predicts a signal peptide or a membrane-spanning region; the Human Protein Atlas places it where antibodies can reach. PROTAC: ubiquitination databases record sites on it; its protein half-life has been measured.
Gene: Protein-coding gene on chromosome 10 (75,233,641 to 75,236,075, reverse strand). Ensembl gene ENSG00000165644.
Subcellular location: Membrane
Subcellular location (Human Protein Atlas): Golgi apparatus; Cytosol; Plasma membrane
Gene Ontology:
Molecular function: protein binding; O-methyltransferase activity
Cellular component: mitochondrion; membrane
Genetic constraint (gnomAD): Loss-of-function variants: 35 observed, 23.89 expected, observed/expected ratio (o/e) 1.46, 90% interval 1.11 to 1.87. The synonymous counts are far from expectation, so gnomAD's model fits this gene poorly and the ratio says little. Missense variants: 370 observed, 279.99 expected, observed/expected ratio (o/e) 1.32, 90% interval 1.21 to 1.44. Synonymous variants: 160 observed, 127.82 expected, observed/expected ratio (o/e) 1.25, 90% interval 1.1 to 1.43.
Homologues: Orthologues: chimpanzee COMTD1 (99% identical), rabbit COMTD1 (90% identical), pig COMTD1 (89% identical), dog COMTD1 (87% identical), mouse Comtd1 (85% identical), guinea pig COMTD1 (84% identical), rat Comtd1 (57% identical), zebrafish comtd1 (44% identical), Caenorhabditis elegans comt-4 (32% identical), Caenorhabditis elegans comt-2 (31% identical), Caenorhabditis elegans comt-5 (31% identical), Caenorhabditis elegans comt-3 (29% identical). Paralogues in human: TOMT (19% identical), COMT (18% identical).
Diseases named in the same sentence as COMTD1 in open-access papers:
COMTD1 is named in the same sentence as 10 diseases in open-access papers, as found by Europe PMC text mining. Sharing a sentence is not in itself a finding about the gene and the disease. The quoted sentences say what the papers report.
schizophrenia (3 papers, 2014 to 2022). A major psychotic disorder characterized by abnormalities in the perception or expression of reality. "COMTD1, a putative O-methyltransferase, has been shown to be differentially methylated in schizophrenia patients, leading to its altered transcription." (PMID 35641855, 2022). "Of these genes, COMTD1 has been shown to be differentially methylated in schizophrenia patients, which would lead to altered transcription of this gene." (PMID 32497066, 2020). "Among these genes were HTR1E, COMTD1 and SLC6A3, which have previously been found to be associated with schizophrenia." (PMID 24399042, 2014).
cardiac hypertrophy (1 paper, 2023). "COMTD1, which is known to be associated with cardiac hypertrophy, is first discovered to be related to the prognosis of ESCC." (PMID 37405477, 2023).
melanoma (1 paper, 2023). A malignant, usually aggressive tumor composed of atypical, neoplastic melanocytes. "Our findings that COMTD1 localizes to mitochondria in immortalized melanocytes and that inactivation of Comtd1 in a mouse melanoma cell line alters the pattern of mitochondrial metabolites provides the first evidence that COMTD1 regulates mitochondrial metabolism." (PMID 37068079, 2023). "To assess the impact of COMTD1 on cellular metabolism and explore links between metabolism and melanogenesis, we used CRISPR/Cas9-mediated gene targeting to generate a Comtd1 knockout (KO) in the pigmented mouse B16F10 melanoma cell line." (PMID 37068079, 2023).
cancer (1 paper, 2026). A tumor composed of atypical neoplastic, often pleomorphic cells that invade other tissues. "Evidence surrounding immune cell infiltration and the general landscape of the GBM TME in COMTD1-deficient cancer is sparse." (PMID 41139700, 2026). "Nevertheless, COMTD1 has been associated with high-risk cancer patients that generally exhibit lower immune effector tumor infiltration." (PMID 41139700, 2026).
tumor (1 paper, 2023). "The Wilcoxon rank-sum test was used to evaluate expression levels, and we found that MIDN, COMTD1, and RAP2B were highly expressed in tumor tissues and lowly expressed in normal tissues." (PMID 37405477, 2023).
COMTD1 also shares sentences with these, for which no sentence is quoted: infection (1 paper); leiomyoma (1); migraine (1); renal fibrosis (1); Uterine leiomyoma (1).